ESR1 (estrogen receptor 1)
Diseases named in the same sentence as ESR1 in open-access papers (continued):
Sharing a sentence is not in itself a finding about the gene and the disease.
breast cancer (continued). "As to phthalates, treatment of human breast cancer MCF7 cells with BBP led to the demethylation of estrogen receptor (ESR1) promoter-associated CpG islands, indicating that altered ESR1 mRNA expression by BBP is related to aberrant DNA methylation in the promoter region of the receptor gene." (PMID 22949852, 2012). "Breast cancers classified as “triple-negative” by clinical diagnostic markers (ESR1, PGR, and HER2 negative) are heterogeneous in their clinical behavior, morphology, and molecular biology." (PMID 23173005, 2012). "Indeed, in female breast cancer ESR1 promoter hypermethylation has been correlated with poor prognosis." (PMID 22765268, 2012). "Therefore a non-replication of a particular variant must be considered inconclusive and warrant further investigation as demonstrated in a recent study of breast cancer at the ESR1 locus." (PMID 21853121, 2011). "Importantly, Pandey and Picard recently demonstrated that miR-22 targets and reduces ESR1 mRNA in breast cancer cells in vitro." (PMID 21223560, 2011). "Importantly, the association of PPARGC1B as well as its synergistic interaction with ESR1 was only observed in breast cancer patients with ER-positive tumors, as would be expected according to the biochemical mechanism of interaction." (PMID 21269472, 2011). "Approximately two-thirds of breast cancers are ESR1-positive." (PMID 22414275, 2011). "Moreover, it has been proved that IGF1R serves as an anchor for ESR1 in the plasma membrane of breast cancer cells." (PMID 21974810, 2011). "Therefore, the presence of ESR1 correlates with increased disease-free survival and a better prognosis when compared to ESR1-negative breast cancers." (PMID 22414275, 2011). "Although the list of hypermethylated genes involved in the tumorigenesis of breast cancer has increased, much of the focus has remained on the estrogen receptor alpha (ESR1) and progesterone receptor (PGR) as these proteins have been implicated in breast cancer development and progression." (PMID 22220212, 2011). "Women carrying both PPARGC1B (rs2340621) and ESR1 (rs7761846) risk genotypes (GA/AA and CT/CC) had a much higher risk for breast cancer than noncarriers (GG and TT) (OR = 1.94, P = 2.03 × 10-6)." (PMID 21269472, 2011). "However, increased levels of oestradiol have been shown to decrease levels of ESR1 in breast cancer, and in normal breast tissue in monkeys and in mice." (PMID 20799965, 2010). "Instead, the identification of genes following a bimodal distribution, reflecting ESR1 expression in breast cancer cohorts, which are epithelial-compartment specific, may present a more robust strategy to develop an ER classifier." (PMID 21152022, 2010). "To provide a higher level of evidence for DC-SCRIPT mRNA expression as a prognostic marker, we now report on DC-SCRIPT expression and its significance in a retrospective validation study of 1,505 breast cancer patients with known ESR1, ESR2, and PGR expression levels." (PMID 21122099, 2010). "To date, the only SNP associated with breast cancer risk with genome-wide statistical significance (P < 10-7) coming from candidate gene approaches is CASP8; more equivocal evidence has been reported for SNPs in TGFB1 and ESR1, among others." (PMID 21194473, 2010). "Comprehensive tag-SNP and meta-analyses found little evidence of breast cancer risk variants in the ESR1 gene itself." (PMID 20661439, 2010). "By this approach, we consistently observed in all the three cohorts that the level of SPP1 and ALCAM mRNA expression enables the discrimination of good vs bad outcome in all ‘high-risk’ breast cancer patients showing low or no ESR1 and HER2 expression." (PMID 20736952, 2010). "Additionally, we found, that some of the genes with subtype-specific expression or co-expression with oestrogen receptor 1 (ESR1) in breast cancer were targets of PRC2 in ES cells." (PMID 20565864, 2010).
breast cancer (continued). "In addition, and central to the understanding of cancer progression, common risk alleles showed differential influence according to ERα tumor status, and variation in the locus encoding for ERα, ESR1, also influences risk of breast cancer." (PMID 21124932, 2010). "Interestingly, in vitro studies in breast cancer cell lines have demonstrated that miR-206 represses the translation of ESR1 mRNA." (PMID 19806225, 2009). "APC was hypermethylated in 29%, RASSF1A in 35% and ESR1 in 20% of breast cancer cases." (PMID 19367284, 2009). "Interestingly a down-regulation was consistently reported for ESR1, a gene playing a major role in clinical management of breast cancer." (PMID 19930681, 2009). "Previous studies described how these genes are coordinately expressed with ESR1 in breast cancers." (PMID 19615102, 2009). "Analysis of the 52 tagSNPs in ESR1 (including the PvuII, XbaI, codon 243 and codon 325 SNPs) did not reveal any association with breast cancer risk, NPI or breast cancer survival whose statistical significance withstood multiple testing correction." (PMID 18271972, 2008). "Gene expression data from the microarray analysis of 92 primary breast tumors (from the UNC Microarray Database) were analyzed for expression of the six genes (CEACAM6, CDH1, CST6, ESR1, LCN2, and SCNN1A) whose loss characterizes the hypermethylator phenotype among breast cancer cell lines." (PMID 18221536, 2008). "With regard to breast cancer risk or survival, a number of single nucleotide polymorphisms (SNPs) have been studied in the ESR1 gene, yet none have previously been investigated in the EGF gene." (PMID 18271972, 2008). "A multi-locus analysis of five adjacent tagSNPs suggested a region in ESR1 (between rs3003925 and rs2144025) for association with breast cancer risk (p = 0.001), but the result did not withstand adjustment for multiple comparisons (p = 0.086)." (PMID 18271972, 2008). "In this regard, revealing the precise mechanisms of degradation of ESR1 with respect to the UPS might further improve the effectiveness of such compounds for the treatment of breast cancer." (PMID 19007432, 2008). "Compounds that affect the interactions of E3 ligases, coactivators and proteasome subunits in ESR1-regulated complexes on promoters could work as anti-breast cancer agents." (PMID 19007432, 2008). "Gene variants in steroid hormone related genes, ESR1, ESR2, PGR, and HSD17B1 have been identified to be associated with either an increased or decreased risk of breast cancer; however, the exact associations remain unclear." (PMID 21655371, 2008). "In fact, it has been shown that ESR1 protein overexpression is common in breast cancer." (PMID 18271972, 2008). "Many anti-breast cancer drugs are involved in degradation of the estrogen receptor (ESR1)." (PMID 19007432, 2008). "A dominant molecular characteristic of the breast cancer samples is ER-α (ESR1) status." (PMID 17845722, 2007). "Microarray profiling of 101 RNA samples showed an average 65-fold range in ESR1 transcript levels across the entire collection of ER-positive breast cancers, with the older cohort showing significantly higher ESR1 levels as compared with the younger cohort, consistent with earlier biomarker studies." (PMID 17850661, 2007). "Other important genes include two breast cancer related genes, namely, the F2R gene, a matrix metalloprotease-1 receptor that promotes invasion and tumorigenesis of breast cancer cells; and PPAR binding protein, coactivator of ESR1 and overexpressed in breast cancer." (PMID 19458770, 2007). "The four different ESR1 probes on the array defined two primary ESR1-associated probe set clusters, including genes (for example, GATA3, KRT8, KRT18) commonly used to define luminal-type breast cancers." (PMID 17850661, 2007). "The findings of this study indicate that specific polymorphisms in the CYP1B1, ESR1, and ESR2 genes may play a role in progression of BBD to breast cancer among Caucasian women." (PMID 16808847, 2006).
breast cancer (continued). "The results indicate that specific polymorphisms in the CYP1B1, ESR1, and ESR2 genes may play a role in progression of BBD to breast cancer among Caucasian women." (PMID 16808847, 2006). "Furthermore, ESR1, the gene that encodes the estrogen receptor (ER) along with pioneering transcription factor FOXA1, is well established factors in hormonally dependent breast cancer." (PMID 41363728, 2026). "A total of 354 consecutive LB samples from breast cancer patients progressing on ET analyzed with the HS2-Mamma-LIQ NGS assay revealed 154 samples (43%) with an alteration in the ESR1 LBD, and 145 samples (41%) were found to have at least one ESR1 hotspot mutation." (PMID 40282442, 2025). "Furthermore, YBX1 and ESR1 serve as biomarkers for adverse outcomes in breast cancer patients." (PMID 40799245, 2025). "Indeed, the recent EMBER-3 trial demonstrated that imlunestrant, a novel oral selective estrogen receptor degrader, showed superior efficacy compared to standard endocrine therapy in endocrine therapy-pretreated/ER+/HER2- advanced breast cancer patients harboring ESR1 mutations." (PMID 40740245, 2025). "Thus, the ability to suppress the activity of both wild-type and ESR1-mutated ERs may constitute a particularly effective therapeutic approach, especially in patients with pre-treated ER+/HER2– breast cancer." (PMID 40598566, 2025). "Notably, despite the low expression of ESR1, the estrogen response pathway still showed significant enrichment in tumor regions, emphasizing the power of pathway-based analyses to refine breast cancer classification." (PMID 40162205, 2025). "Analysis of biopsies from heavily pretreated, ER‐positive breast cancers revealed tumors lacking detectable ESR1 mutations frequently adopted a mixed‐lineage phenotype, indicative of lineage plasticity, whereas ESR1‐mutant tumors largely preserved their luminal identity and ERα dependency." (PMID 41415713, 2025). "The results of the analysis of the CTC number and ESR1 and PIK3CA mutations in blood collected from 179 patients with metastatic breast cancer show that ESR1 mutations are more frequent in patients with advanced luminal breast cancer regardless of the type of the treatment." (PMID 40076662, 2025). "Additionally, their activity in ESR1-mutant clones makes them especially relevant for women with atypical hyperplasia or lobular carcinoma in situ (LCIS), who may harbor occult genomic alterations." (PMID 41300964, 2025). "This combination in metastatic breast cancer is limited by some mutations in ESR1 which encodes ERα, such as the ESR1 Y537S or D538G mutation, which can activate estrogen signaling in the absence of estrogen and may promote PI3K pathway activation in breast cancer." (PMID 38920692, 2024). "Primarily, ESR1 expression is associated with various pathological aspects of breast cancer; however, it is worth noting that ESR1 positivity is associated with a better prognosis in these patients and could be targeted by specific estrogen receptor modulators." (PMID 38279245, 2024). "The cells of origin of BRCA1-associated mammary tumours, the mammary luminal epithelial estrogen receptor (ESR1)-negative stem/progenitor population, express the c-KIT (or KIT) receptor tyrosine kinase at high levels, as well as its downstream pathway member, the SRC-family kinase LYN." (PMID 38149669, 2024). "Interestingly, ESR1 is a current therapeutic target in breast cancers." (PMID 39207857, 2024). "Although several studies have confirmed that mutation or amplification of the ESR1 gene is not common in breast cancer samples, elevated expression of ERα could be more common in luminal breast tumors than in normal breast tissues." (PMID 36271315, 2023). "The ESR1 N532D mutation has not yet been described in breast cancer." (PMID 36823365, 2023).
breast cancer (continued). "Previously, FSRH, INHA, ESR1, and BMP15 gene polymorphisms have been studied with regard to the conditions of the female reproductive system, including polycystic ovary syndrome, poor ovarian response, POI, breast cancer, and endometriosis, as well as male infertility." (PMID 37239044, 2023). "Subgroup analysis of the EMERALD clinical trial identifies clinical benefit with elacestrant in patients who had received prior fulvestrant independent of the mutational status of the ESR1 gene, supporting its potential utility in treating refractory HR+breast cancer." (PMID 37318638, 2023). "Thus, progesterone opposes the estrogen–ER signaling at the DSCAM-AS-1–ESR1 genomic axis via two synergistic modes: it reduces the expression of DSCAM-AS1 and elevates the expression of miR-130a, which interacts with both DSCAM-AS1 and 3′-UTR of ESR1 in breast cancer cells." (PMID 37395734, 2023). "Moreover, in some cases, the results dictate the application of specific treatment regimens, and this is particularly true of early-stage breast cancer where expression of estrogen receptor α (ERα, ESR1) in mammary tumors usually results in treatment with endocrine therapies." (PMID 36982239, 2023). "In this study, we sought to detect ESR1 mutations using ddPCR in non-metastatic ER+ breast cancer." (PMID 35501333, 2022). "To determine if the genes overexpressed in ESR1 Y537S cells are also overexpressed in tumors from breast cancer patients harboring ESR1 mutations, we integrated the RNA-Seq data from our MCF-7 Y537S cells with previously reported transcriptomic data of tumors from ESR1 mutant breast cancer patients." (PMID 35881485, 2022). "In breast cancer, Spanish guidelines suggest that an optimal gene panel should detect AKT1, PIK3CA, PTEN, and ESR1 mutations and FGFR1 amplification, in addition to studying estrogen receptor, progesterone receptor, HER2, and BRCA1/2, although NGS is still only considered a research tool." (PMID 35055387, 2022). "Using a transcriptome dataset for 51 breast cancer cell lines including luminal, ERBB2-amplified, basal and claudin-low lines, we determined whether expression of CA12 is also associated with that of ESR1 and how it compares with PGR expression." (PMID 36358871, 2022). "Thus, if ESR1 gene expression is increased this may lead to greater proliferation of breast tissue, culminating in greater MBD and increased breast cancer risk." (PMID 35422057, 2022). "The authors noted that variants in the ESR1 region of SNPs associated with endometriosis risk were not the same as the ESR1 SNPs associated with age at first birth, age at menarche or breast cancer which is something that needs to be born in mind when linking risks to pathways." (PMID 35514537, 2022). "A similar concordance level was observed for advanced breast cancer patients, where an overall concordance of up to 95% (negative and positive) was observed for the detection of mutations from the four major driver genes of breast cancer—PIK3CA, ESR1, AKT1, and HER2." (PMID 35805046, 2022). "A large number of studies have confirmed that ESR1 can be used as a transcription factor to regulate many complex physiological processes of the human body and plays an important role in the treatment of many cancers, such as breast cancer, prostate cancer, and endometrial cancer." (PMID 35686089, 2022). "High correlation between CA12 and ESR1 expression is reproducible in the TCGA Firehose Legacy dataset comprising 960 breast tumor transcriptomes (Pearson correlation coefficient of 0.80) and in the 1904 breast cancer samples from the METABRIC dataset (Pearson correlation coefficient of 0.79)." (PMID 36358871, 2022). "In addition, hypermethylation of RPRM related to ERα (ESR1) has been observed in several cancers such as breast cancer, which is overexpressed in cells treated with BPA in the present study, and even more so in treatments with naringenin + BPA, FEN, and FEN + BPA." (PMID 36235125, 2022).
breast cancer (continued). "Pathogenic ESR1 mutations are a common mechanism of acquired but not intrinsic resistance to endocrine therapy and may not warrant universal testing of primary breast cancer populations." (PMID 35959983, 2022). "NCCN Guidelines for Breast Cancer V.1.2021 include NGS and comprehensive genomic profiling (CGP) as a method of detecting actionable mutations and fusions such as BRCA1/2 mutations, PIK3CA mutations, ESR1 mutation, HER2 mutation, MSI-H status, and deficient mismatch repair (dMMR)." (PMID 35804935, 2022). "In addition, we discovered that ESR1 regulates RP4-5681C11.4 in breast cancer." (PMID 36120580, 2022). "Moreover, it was indicated that, in the case of some breast cancer tissues, ESR1 expression might be modulated not only by DNA methylation at T-DMRs and promoter regions but also by different mechanisms that require clarification in future studies." (PMID 34064195, 2021). "Additionally, x-ray crystal structures of SERMs and SERDs in complex with Y537S ERα LBD are also needed to uncover whether specific ligand-induced H12 conformations correlate with improved potencies in breast cancers harboring ESR1 mutants." (PMID 33980285, 2021). "Cell culture experiments in breast cancer cells indicated that a direct interaction between GR and esr1, which is mediated via the transcription factor activator protein 1 (AP-1), has an important role in controlling esr1 activity and GR-mediated inhibition of E2-induced cell proliferation." (PMID 34436443, 2021). "Breast cancer is a complex and highly heterogeneous disease which is typically classified in molecular subtypes according to the expression of specific factors such as estrogen receptor (ESR1), progesterone receptor (PGR) and human epidermal growth factor receptor 2 (HER2)." (PMID 34809697, 2021). "Similar result was observed in breast cancer, where it was possible to stratify a patient cohort based on regulon activity.In the same work, the authors have shown that the pharmacological inhibition of estrogen receptor drastically suppresses the ESR1 regulon." (PMID 33924679, 2021). "Genetic fine-mapping studies in breast cancer suggest that cis-regulatory risk variants may disrupt DNA binding affinities of TFs, particularly for known master regulators FOXA1 and ESR1, altering the regulation of gene expression and affecting breast cancer risk." (PMID 34518541, 2021). "Breast-specific markers as PALB2 or ESR1 were expressed independently of the culture state, although both genes showed a higher relative expression in CTCs from cultured samples (p = 0.03 and 0.06, respectively) suggesting that mammary tumor cells were proliferating in the culture." (PMID 34071445, 2021). "Moreover, in a first line randomized phase III double-blind study (MONARCH 3) for ESR1+/HER2− advanced breast cancer, abemaciclib presented a better hematological tolerability compared to palpociclib and ribociclib, and achieved impressive results in terms of PFS and objective response rate (ORR)." (PMID 34445095, 2021). "In addition to the expected ESR1 hotspot mutations, ERBB2 and NF1 were the genes, mostly mutually exclusive, with the greatest difference in mutational frequency between pre- and post-hormonal therapy for HR + HER2− breast cancers." (PMID 33477469, 2021). "However, there are exceptions, for example, we could identify ESR1 differential activity in luminal breast cancers purely from proteomic data, using expression relations." (PMID 34179843, 2021).